CA2 (carbonic anhydrase 2)
Diseases named in the same sentence as CA2 in open-access papers (continued):
Sharing a sentence is not in itself a finding about the gene and the disease.
brain injury (1 paper, 2021). Acute and chronic (see also brain INJURIES, CHRONIC) injuries to the brain, including the cerebral hemispheres, CEREBELLUM, and brain STEM. "We previously identified a short peptide aptamer from collapsin response mediator protein 2 (CRMP2), designated the Ca2+ channel-binding domain 3 (CBD3) peptide, that conferred protection against excitotoxicity and traumatic brain injury." (PMID 34362425, 2021).
breast tumor (1 paper, 2013). "The effects of 1,25(OH)2D3 0.5nM on the expression of CYP24A1, DPP4, IL1RL1, CD14, CA2 and BMP6, were further explored in breast tumor derived cells, representing the epithelial and stromal compartments, using RT-qPCR." (PMID 23497279, 2013).
cerebral malaria (1 paper, 2011). A sequestration of Plasmodium falciparum in the brain, which can cause coma and/or seizures. "However, it appears unlikely that polymorphism of C9orf7 is primarily associated with cerebral malaria, since Ca2+ channel is not currently implicated in the pathogenesis of cerebral malaria." (PMID 22168261, 2011).
Chagas disease (1 paper, 2023). A parasitic infection caused by Trypanosoma cruzi. "The most abundant antigenic clusters recognized by patients correspond to the surface antigen CA-2 (B13) followed by the microtubule associated antigen, which highlights the value of these epitopes in Chagas disease diagnosis." (PMID 36608168, 2023).
co-infection (1 paper, 2022). "As a result of an acid–base imbalance, the rupturing of cell membranes ensures effective virulence, which is detrimental for cellular parasites, whose co-infection significantly increases CA2 expression, as observed in this study and in data in the literature." (PMID 35457192, 2022).
cystic fibrosis (1 paper, 2017). Autosomal recessive disorder caused by pathogenic variants in the CFTR gene (cystic fibrosis transmembrane conductance regulator), which encodes a chloride and bicarbonate channel expressed in epithelial cells, and follow the diagnosis criteria. "Anoctamin 1 (ANO1/TMEM16A) was identified as the major Ca2+-activated Cl− channel in airway epithelial cells, and we recently demonstrated that downregulation of the anoctamin 1 channel in cystic fibrosis patients contributes to disease severity via an unknown mechanism." (PMID 28955034, 2017).
dengue (1 paper, 2021). "Indeed, CA2 shows higher expression levels in samples with Zika compared with those with dengue diagnosis (p-value < 0.05), consistent with the proteomics results for the 2016/2017 cohort." (PMID 33582300, 2021). "While CA2 has not been linked to dengue or Zika virus infection, there is evidence for its role in brain development and function, as well as respiratory-distress syndrome in infants." (PMID 33582300, 2021).
Diaphyseal sclerosis (1 paper, 2014). An elevation in bone density in one or more diaphyses. "TNFSF11 presents phenotypic similarities with CA2 for extramedullary hematopoiesis (HP:0001978), cranial nerve compression (HP:0001293), diaphyseal sclerosis (HP:0003034), hepatosplenomegaly (HP:0001433) and cranial hyperostosis (HP:0004437)." (PMID 25420641, 2014).
fibrosis (1 paper, 2025). the formation of excess fibrous connective tissue in an organ or tissue in a reparative or reactive process. "Myocardial fibrosis scores were heightened in C0 NAP1L1+ TCs (stage I), C1 CA2+ TCs (stage 0), C1 CA2+ TCs (stage I), and C0 NAP1L1+ TCs (stage II)." (PMID 40842994, 2025).
foot and mouth disease (1 paper, 2021). A viral infectious disease that results in infection in cattle and swine, has material basis in foot-and-mouth disease virus, which is transmitted by contaminated fomites, or transmitted by ingestion of food contaminated with infected meat or animal products. "The EV-A types identified included coxsackievirus A2 (CA2), CA4, and EV71, typically associated with hand, foot and mouth diseases." (PMID 34301271, 2021).
gastritis (1 paper, 2025). Inflammation of the stomach. "A different model, designed to predict cancer or preneoplasia vs. healthy or gastritis, yielded an even higher mAUROC of 83.9% (73.9–93.9% (95% CI)) and was based on the plasma concentrations of ARG1, HPT, CA2, MAN2A1, and LBP." (PMID 41155404, 2025).
Headache (1 paper, 2022). Cephalgia, or pain sensed in various parts of the head, not confined to the area of distribution of any nerve. "For example, headache was positively correlated with CA2 and fibronectin 1 (FN1) (ρs > 0.42, p value < 0.05)." (PMID 35668171, 2022).
Hepatic steatosis (1 paper, 2025). Steatosis is a term used to denote lipid accumulation within hepatocytes. "The top predictive proteins for hepatic steatosis included TNC, GAPDH, CA2, and C9, underscoring the role of inflammatory mediators and lipid-handling proteins in this condition." (PMID 40981199, 2025).
Infertility (1 paper, 2018). "For instance, mutations in components of sperm-specific CatSper Ca2+ channels entail infertility by impairing hyperactivated sperm motility without interfering with their development (42, –, 45)." (PMID 29880644, 2018).
inflammatory skin disease (1 paper, 2020). Inflammatory skin disorders covers a broad category that includes many conditions ranging in severity, from mild itching to grave medical health complications These disorders are common in people of all ages and races. "In addition, altered CA2 expression has been linked to inflammatory skin diseases." (PMID 32602849, 2020).
influenza (1 paper, 2021). An acute viral infection of the respiratory tract, occurring in isolated cases, in epidemics, or in pandemics; it is caused by serologically different strains of viruses (influenzaviruses) designated A, B, and C, has a 3-day incubation period, and usually lasts for 3 to 10 days. "It is noteworthy that most influenza antibodies produced by immunization or infection are directed against five antigen sites on the HA1 globular head, Ca1, Ca2, Cb, Sa, and Sb48–50." (PMID 34966175, 2021).
Intellectual disability (1 paper, 2024). "In a recent study, Gudenas and Wang found that the expression of RP11-588H23.3 is highly correlated with CA2, a key gene associated with intellectual disability." (PMID 39405331, 2024).
lobular carcinomas (1 paper, 2007). "Several genes encoding proteins involved in actin, calcium and metal ion binding were downregulated (MYBPC1, DST, PIP, CA2), and some genes with the same function (BGN, ADAM12) were upregulated in lobular carcinomas." (PMID 17389037, 2007).
lymphedema (1 paper, 2021). Excess fluid collection in tissues, causing swelling. "Considering that hemoglobin may be easily influenced during venipuncture and that the focus of this study was to investigate the oxidative stress associated with lymphedema, we chose four other protein targets (CAT, PRDX2, CA1, and CA2) for further validation of their expression by ELISA." (PMID 33917571, 2021).
macular degeneration (1 paper, 2025). Loss of vision in the central portion of the retina (macula), secondary to retinal degeneration. "•Proteins linked to macular degeneration (CA1, CA2, HBA1) and PRP treatment (APOB, CST6) were identified." (PMID 40118382, 2025). "Additionally, proteins associated with macular degeneration (CA1, CA2, and HBA1) were uncovered, providing new insights into overlapping mechanisms between DR and other retinal diseases." (PMID 40118382, 2025).
memory impairment (1 paper, 2021). "The CA2 is highly expressed with the vasopressin 1b (Avpr1b) receptor, and the knockout of Avpr1b results in social memory impairment, whereas targeted activation of CA2 Avpr 1b during the acquisition period could enhance social memory, demonstrating their association." (PMID 34385906, 2021).
Myocardial fibrosis (1 paper, 2018). "We next assessed myocardial fibrosis and Ca2+ cycling proteins, which are key determinants of diastolic and systolic dysfunction." (PMID 29208771, 2018).
myocarditis (1 paper, 2024). Myocarditis is a condition that is characterized by inflammation of the heart muscle (myocardium). "We investigated Ca2+ regulatory proteins that mediate the detrimental effects of myocarditis on Ca2+ homeostasis." (PMID 38650023, 2024).
necrotizing enterocolitis (1 paper, 2018). Necrotizing enterocolitis (NEC) is a devastating disease that affects mostly the intestine of premature infants. "Two variants of the CA synthesis gene cluster (CA1 and CA2) are found in C. sakazakii isolates, and the ones containing CA2 are associated with neonatal meningitis and necrotizing enterocolitis." (PMID 30154778, 2018).
neuropathy (1 paper, 2017). A disorder affecting the nervous system that manifests with pain, tingling, numbness, and/or muscle weakness. "TRPA1 is a Ca2+-permeable ion channel involved in many sensory disorders such as pain, itch and neuropathy." (PMID 28332600, 2017).
pulmonary hypertension (1 paper, 2022). Increased pressure within the pulmonary circulation due to lung or heart disorder. "The avoidance of pulmonary hypertension is due to the increased expression of GNG2 and CA2 and the decreased expression of TAGLN and MPO, and the increased vascular permeability is due to the increased expression of GNG2 and the decreased expression of GSN." (PMID 36009723, 2022).
renal tubular dysfunction (1 paper, 2014). "TBCE and CA2 are not functionally associated, but both genes are associated phenotypically with renal tubular dysfunction (HP:0000124) and increased bone mineral density (HP:0011001)." (PMID 25420641, 2014).
Salmonella Infections (1 paper, 2021). Infections with bacteria of the genus SALMONELLA. "In a few cases, 7-dpi upregulation mediated by the SE challenge and/or supplement in S-II, S-III, and S-IV reached a factor of ~400 to ~500 (CA2) and even ~3100 (BPIFB3), which was comparable to the maximal expression of various genes in response to Salmonella infection in other studies." (PMID 33535430, 2021).
schistosomiasis (1 paper, 2015). An infectious disease caused by parasitic trematodes of the genus Schistosoma that colonize human blood vessels and release eggs that can cause granulomatous reactions leading to acute (swimmer's itch or acute schistosomiasis syndrome) or chronic disease. "Indeed, some of these antigens are protective in animal challenge models of schistosomiasis; for example, vaccination with and the Ca2+-activated protease, calpain (AY814430), induces 64% in baboons." (PMID 25999951, 2015).
Stroke (1 paper, 2012). Sudden impairment of blood flow to a part of the brain due to occlusion or rupture of an artery to the brain. "Ca2+-ATPase-encoding Atp2b2 plays a major role in clearing Ca2+ from the neuronal cytoplasm and was downregulated after stroke." (PMID 23251410, 2012).
Takotsubo syndrome (1 paper, 2024). "Emotional stress, often a precursor to Takotsubo syndrome, can trigger spikes in adrenergic activity, leading to Ca2+ overload and subsequent impacts on Ca2+ handling proteins through cAMP-mediated activation of protein kinase A20." (PMID 39487225, 2024).
Tinnitus (1 paper, 2022). Tinnitus is an auditory perception that can be described as the experience of sound, in the ear or in the head, in the absence of external acoustic stimulation. "Here, we chemogenetically decrease activity of a subgroup of DCN neurons, Ca2+/Calmodulin kinase 2 α (CaMKII α)-positive DCN neurons, using Gi-coupled human M4 Designer Receptors Exclusively Activated by Designer Drugs (hM4Di DREADDs), to investigate their role in noise-induced tinnitus." (PMID 35550106, 2022).
trauma (1 paper, 2016). "It has long been recognized that head trauma induces an excessive release of glutamate and prolonged activation of Ca2+ ion channels." (PMID 27091009, 2016).
Ventricular arrhythmia (1 paper, 2019). "Given the crucial role of Ca2+-handling in action potential generation and cardiac contraction, Ca2+ channels and Ca2+ handling proteins represent promising targets for suppression of ventricular arrhythmias." (PMID 31653119, 2019).
cancer (107 papers, 2006 to 2026). A tumor composed of atypical neoplastic, often pleomorphic cells that invade other tissues. "ANXA4, a Ca2+-dependent membrane-binding protein modulating membrane permeability has been linked to many cancer types, however, its association with iNPH remains elusive." (PMID 37277809, 2023). "Specifically, various Ca2+ channels have been associated with the behavior of cancer cells and the physiopathology features of cancer." (PMID 36499622, 2022). "On the contrary, tumour acidosis modulation shows a higher variability, determining loss-of-function of specific Ca2+-permeable ion channels expressed not only by cancer cells but also by immune cells, or potentiation or activation of others." (PMID 35806388, 2022). "Annexin A1 (ANXA1), a Ca2+-regulated phospholipid-binding protein, has been demonstrated to be implicated in the progression and prognosis of many cancers." (PMID 34991599, 2022). "Overexpression of Ca2+ channels, pumps, or exchangers is associated with cancer prognosis." (PMID 38510751, 2024). "Previous studies suggested that NDRG1 could inhibit proliferation and induce apoptosis of cancer cells by regulating Bcl-2 and Ca2+-associated proteins and epithelial–mesenchymal transition (EMT)." (PMID 35795037, 2022). "Target mapping implicated clinically relevant proteins such as carbonic anhydrase 2 (CA2), PARP1, and PPARA, associated with metabolic disorders, neurodegeneration, and cancer." (PMID 42221505, 2026). "For cancer vs. non-cancer prediction, the best-performing biomarker was the plasma concentration of CA2 (mAUROC = 78.1%, 61–95.1% (95% CI))." (PMID 41155404, 2025). "In this Outlook, we aim to providea concise overview of contemporaryresearch on the regulation of Ca2+ channels with CMs formodulating biological functions, including cancer and thrombolysistherapy, remote neurostimulation, and glycemic management." (PMID 41476766, 2025). "In pathological conditions like cancer, Ca2+ signalling is frequently disrupted due to the dysregulation of various Ca2+ channels, pumps, exchangers, and binding/storage proteins." (PMID 38510751, 2024). "When a normal cell transforms into a cancer cell, there is a significant rearrangement of Ca2+ pumps, Na/Ca exchangers, and Ca2+ channels." (PMID 36905557, 2023). "Among them, several up-regulated genes are known to be involved in the formation of tumor microenvironments (Carbonic anhydrase 2 (CA2)), cancer chemoresistance (Cannabinoid receptor 1 (CNR1), GFRA1) and cancer recurrence after therapy (RGL3)." (PMID 36769365, 2023). "The overexpression and/or overactivity of Ca2+ channels and transporters is a characterizing feature of cancer, yet roles for Ca2+‐dependent downstream effectors are poorly understood." (PMID 38938673, 2023). "Few cancer cells expressed marker genes of differentiated cell types such as CA2 (enterocyte marker) and MUC2 (goblet marker)." (PMID 35974387, 2022). "The differentiated cancer cells had significantly increased the levels of CA2 (a ductal epithelial cell marker), while the levels of CEL (an acinar cell marker) did not change." (PMID 35673567, 2022). "This led to the observation that both CA2 and CAm complex-type N-glycans were increased in the submucosa and in the carcinoma areas mainly close to the invasion site." (PMID 35326703, 2022). "Several reports have identified Ca2+ channels as essential in different cancer stem cells, although the specific roles of SOC remain to be clarified." (PMID 34298643, 2021). "Specifically, the expression of Munc13-4, a Ca2+-dependent Rab-binding protein, is elevated in cancer cells, which combined with the increased Ca2+ levels enhances exosome release from cancer cells." (PMID 34283059, 2021). "Different Ca2+ channels or pumps are potential therapeutic targets in different cancer subtypes, and are correlated with prognosis." (PMID 32629766, 2020).
cancer (continued). "There is a piece of considerable evidence demonstrating that the amount of NKA and Ca2+ channel is increased to exchange the ions at a higher level than that of the normal cells in cancer cells." (PMID 33456676, 2020). "In this review, we summarize the current knowledge on the pathophysiological roles of these Ca2+-permeable channels, with special emphasis on their functional involvement in different cancer types progression." (PMID 32635333, 2020). "TRP channels are Ca2+-selective ion channels involved in cancer development and metastatic spreading by controlling different stages of tumor progression." (PMID 31801263, 2019). "It is reported that any disorders of Ca2+ channels and/or receptors will lead to various diseases, such as cancer." (PMID 29435418, 2018). "Anoctamin-1 (ANO1) acts as a Ca2+-activated Cl− channel in various normal tissues, and its expression is increased in several different types of cancer." (PMID 27212225, 2016). "There was also a trend towards up-regulation of CA2, DPP4 and IL1RL1 in cancer associated fibroblasts." (PMID 23497279, 2013). "This cation, operating as a second messenger, constitutes a positive regulator of cell migration; it is particularly effective in cancer cells, apparently due to its aberrant expression of Ca2+-handling proteins and Ca2+-dependent effectors, either in the form of kinases, proteases, or phosphatases." (PMID 37947651, 2023). "Annexins family (ANXAs), as a Ca2+-dependent phospholipid-binding protein superfamily, participates in a wide variety of biological activities and has been reported to be dysregulated in numerous types of human cancers." (PMID 39290334, 2022). "Due to the essential role of the most studied store-operated Ca2+ ion channel, the CRAC channel, in the co-regulation with Ca2+-dependent K+ ion channels in cancer, we focus initially on its currently known structure/function relationship as well as its individual role in cancer." (PMID 36612099, 2022). "Targeting the altered activities of Ca2+ channels and pumps may present promising chemotherapy for cancer treatment." (PMID 36046147, 2021). "Several selective and non-selective Ca2+-permeable ion channels are implicated in mediating Ca2+ signaling in cancer cells." (PMID 32046188, 2020). "Consequently, it can be concluded that the NKA pump and Ca2+ channels are good targets for cancer therapy." (PMID 33456676, 2020). "Since some of these Ca2+ channels have a role in physiological cell activities, one challenge in drug discovery, affecting these Ca2+ signalling proteins, is to recognise their cancer specific roles." (PMID 31766522, 2019). "Moreover, certain cancers are associated with the up- or down-regulation of specific Ca2+ channels or pumps, leading to the proposal that because Ca2+ channels, pumps and exchangers are modulated by pharmacological agents, they may be targeted for cancer treatment." (PMID 26317541, 2015). "EAC exhibits the enhanced extracellular matrix remodeling (collagens, IGFBP7, PLAU) effects expected in an aggressive form of cancer, as well as evidence of reduced expression of genes associated with mucosal (MUC6, CA2, TFF1) and xenobiotic (AKR1C2, AKR1B10) defenses." (PMID 21829465, 2011). "Changes in the expression or activity of Ca2+ channels and pumps could promote role in cancer." (PMID 31097925, 2019). "However, it remains unclear whether TMEM16A may couple to different Ca2+-permeable ion channels in different cancers." (PMID 28893247, 2017). "CA2 displayed an opposite expression trend to CA9, warranting further investigation of its role in cancer." (PMID 39393173, 2024). "The PDAC cells were divided into three states according to CA2 and CD44 expression levels: “State 1” as CA2(-)CD44(+) CICs, “State 2” as CA2(+)CD44(-) differentiated ductal-like cancer cells, and “State 3” as CD44/CA2-negative cells." (PMID 35673567, 2022).